IL10 (interleukin 10)
Diseases named in the same sentence as IL10 in open-access papers (continued):
Sharing a sentence is not in itself a finding about the gene and the disease.
colitis (continued). "IL-10 deficiency in mice leads to increased endotoxemia-associated mortality during microbial infection and increased susceptibility to autoimmune disorders such as colitis and autoimmune encephalomyelitis." (PMID 27308096, 2016). "Furthermore IL-10 or IL-10R mutations are associated with the increased risk of developing colitis in human IBD patients." (PMID 27308096, 2016). "Our study shows that sodium butyrate ameliorated histological colitis which was associated with a reduction in the amount of IgA-coated bacteria, modified the composition of the microbiome and changed the SCFAs concentration in the colon in IL-10−/− mice." (PMID 27886121, 2016). "Moreover, genetic deficiency of either IL-10 or IL-10R in transgenic mice leads to a breakdown in immune tolerance and immune mediated colitis, representing a well-established murine model for IBD." (PMID 27611574, 2016). "In conclusion, Lcn2 prevented the development of spontaneous colitis in IL-10 deficient mice." (PMID 27734904, 2016). "IL-10–deficient (Il10−/−) and IL-10 receptor (IL-10R)–deficient mice develop enhanced T helper (Th) type-1/Th17 responses to intestinal bacterial antigens, which induce severe colitis." (PMID 27027442, 2016). "Additionally, treatment with a selective S1P1 receptor agonist (SEW2871) improves colitis symptoms in IL-10 deficient mice." (PMID 27656050, 2016). "In addition, the severity of spontaneous colitis in IL-10 knockout mice is increased by Tollip deficiency." (PMID 27741296, 2016). "However, Punit and colleagues reported that TNFR2 deficiency resulted in a greater colitis in il10−/− mice as well as in mouse colitis induced by AOM/DSS treatment." (PMID 27601345, 2016). "In agreement with their transcriptional profile, Th17TGF-β1 cells were significantly less pathogenic than Th17IL-23 cells in a model of experimental colitis, as they induce a transient reduction in weight loss in Rag-/- mice and the production of IL-10 in the intestine." (PMID 27322617, 2016). "IL-10 deficient mice spontaneously develop colitis resembling the pathogenesis of human IBD." (PMID 27308096, 2016). "Furthermore, FO (7% FO w/w in the diet, for 12 weeks) was found to exacerbate colitis and colitis-associated premalignant lesions in IL-10 −/− transgenic mice, spontaneously developing enterocolitis." (PMID 26301240, 2015). "On the contrary, we have previously shown that ibpAB-deficient E. coli paradoxically cause increased inflammatory responses in colitis-prone Il10-/- mice compared with wt mice by unknown mechanisms." (PMID 25798870, 2015). "As a matter of fact, mice deficient for IL-10 develop spontaneous colitis." (PMID 25889561, 2015). "Recent findings regarding increased abundance of enterococci in the intestinal microbiota of patients with inflammatory bowel diseases and induction of colitis in IL-10-deficient (IL-10-/-) mice put a new perspective on the contribution of E. faecalis to chronic intestinal inflammation." (PMID 26067254, 2015). "Moreover, loss of function mutations in the gene of IL-10 or its receptor causes early onset of IBD with refractory colitis and perianal disease." (PMID 26199463, 2015). "Moreover, NS8-induced improvement in murine colitis is associated with the up-regulation of anti-inflammatory cytokine IL-10 in PBMCs and LPS-stimulated murine macrophage cell line RAW264.7." (PMID 26428623, 2015). "Although the molecular mechanisms of how histidine regulates intestinal inflammation have not been fully investigated, we previously demonstrated that oral administration of histidine ameliorated intestinal inflammation in an interleukin-10-deficient cell transfer mouse model of colitis." (PMID 26474176, 2015). "As far as CD is concerned, the relevance of the IL-10 pathway in dampening inflammation was substantiated by the development of severe colitis in infants with mutations of IL-10, IL-10RA, or IL-10RB genes and in mice deficient in IL-10 that underwent spontaneous development of colitis." (PMID 26206376, 2015).
colitis (continued). "In addition, IL-10-deficient mice, which normally develop colitis, are protected from developing severe chronic colitis when a deletion of the NOD2 gene is also introduced into these mice." (PMID 25071778, 2014). "Here we show that IL-17KO mice had increased susceptibility to DSS-induced colitis which was associated with decrease in expression of mRNAs implicated in M2 and/or wound healing macrophages, such as IL-10, IL-1 receptor antagonist, arginase 1, cyclooxygenase 2, and indoleamine 2,3-dioxygenase." (PMID 25254662, 2014). "Similarly, IL-10 is important to prevent colitis in humans, as certain variants of early-onset IBD observed in infants and small children appear to be a monogenic diseases caused by deleting mutations in IL-10 or its receptor." (PMID 24489792, 2014). "Importantly, we demonstrate here that these BregIL-33 cells, when isolated and adoptively transferred into IL-10−/− mice, can block the development of spontaneous colitis in the IL-10-deficient recipients." (PMID 24491821, 2014). "Here we chose to evaluate whether a LV encoding IL-10 was effective in treating or preventing DSS induced murine colitis for three reasons." (PMID 24712338, 2014). "For Cd14, which is involved in the detection of lipopolysaccharides by TLR4, it was later demonstrated that a higher expression by gut epithelial cells is responsible for a lower colitis susceptibility in IL-10-/- mice with a C3H than with a C57BL/6 background." (PMID 23951309, 2013). "However, we found that loss of GC-C results in the accelerated appearance of colitis in IL-10−/− animals." (PMID 24244444, 2013). "Enteococcus faecalis, a commensal bacterium of humans and animals, has shown the capability to induce irritable bowel syndrome (IBS) in IL-10 gene-deficient mice, suggesting that certain enteric microbiota tend to be more opportunistic and can induce colon inflammation." (PMID 23840722, 2013). "In the present study, genetic deletion of GC-C may synergize with loss of IL-10 at an early age to accelerate the appearance and progression of colitis." (PMID 24244444, 2013). "The same observation has been reported in C3H and C57BL/6 mice and was associated with a strain-specific susceptibility to microbiota-driven colitis: interleukin 10-deficient mice with a C3H background are susceptible whereas the C57BL/6 background renders the mice colitis resistant." (PMID 23951309, 2013). "Analysis of quantitative trait locus mapping of C3H/HeJBir mice backcrossed with IL-10 KO mice identified several potential colitogenic loci on chromosome 3, 1, 2, 8, 17, and 18, named, respectively, cytokine deficiency-induced colitis susceptibility 1–6 (Cdcs1–6)." (PMID 24062746, 2013). "Indeed, genetic deficiency of IL-10 is associated with disruption in gut homeostasis and severe colitis in mice." (PMID 23730302, 2013). "In addition, recent evidence from the IL10−/− colitis model demonstrated the importance of diet-induced alterations in the intestinal microbiota associated with the selection of the colitis-relevant pathobiont Bilophila wadsworthia." (PMID 23977107, 2013). "However, in a murine colitis model, numbers of Lactobacilli remained unaffected, while IL-10 gene deficient mice have deceased levels of colonic Lactobacilli." (PMID 22848694, 2012). "In this study we investigated the extent to which fecal Lcn-2 can serve as a sensitive and non-invasive biomarker of intestinal inflammation using a well-studied murine models of dextran sulfate sodium (DSS) induced colitis and spontaneous colitis in IL-10 deficient mice." (PMID 22957064, 2012). "Finally, the pro-inflammatory cytokines TNF-α, IFN-γ, IL-1β and IL-6, and anti-inflammatory cytokine IL-10 have been implicated in experimental and human colitis." (PMID 22844504, 2012).
colitis (continued). "In a follow up study, using a different model of colitis-associated colonic carcinogenesis, IL-10−/− mice in a 129/SvEv background were infected with H. typhlonius, thus accelerating the colonic inflammation that the IL10−/− develop spontaneously and promoting colonic carcinogenesis." (PMID 22511958, 2012). "DSS administration induced moderate colitis (2.2 ± 0.3) in WT mice to severe cases (3.6 ± 0.5) in IL-10-deficient mice possibly due to more severe immune reaction to overgrowth of gut microbial due to the lack of protective IL-10 and overactivation of macrophages and inflammatory cells." (PMID 22315509, 2012). "Finally, we tested the impact of IL-10 deficiency and colitis development in the two major immunological activities that take place at the gut mucosa: secretory IgA (sIgA) production and oral tolerance induction." (PMID 22400037, 2012). "In addition, fecal Lcn-2 marks the severity of spontaneous colitis development in IL-10 deficient mice." (PMID 22957064, 2012). "As an alternative to chemically induced colitis, several models helped to gain valuable insight into the underlying pathology of IBD, such as the model based on transfer of CD45RBHi CD4+ T cell to immunodeficient recipients or the development of colitis in IL-10 deficient mice." (PMID 23226271, 2012). "Additionally, the effects of histidine were examined in vivo using an IL-10-deficient (IL-10−/−) cell transfer colitis model, and histidine exerted a protective effect against colitis." (PMID 22384111, 2012). "Spontaneous colitis develops sporadically over several months, but piroxicam treatment will induce rapid and uniform disease in IL-10-deficient mice, which likely occurs as a result of increased colonic epithelial cell apoptosis causing a loss of barrier function to inflammatory microbial stimuli." (PMID 23053394, 2012). "Furthermore, as an in vivo correlate, 11R-VIVIT ameliorated active colitis in piroxicam-treated IL-10 deficient (Il10−/−) mice." (PMID 22479554, 2012). "However, it has not been studied in detail if this polymorphism indeed affects IL-10 – IL-10R interactions in colitis patients." (PMID 21464967, 2011). "Another S1P receptor agonist, KRP-203, was also useful for colitis in IL-10 deficient mice." (PMID 21931623, 2011). "The anti-inflammatory cytokine IL10 has long been proposed to limit intestinal inflammation, and genetically engineered IL-10 deficient mice develop spontaneous colitis suggesting it might serve as a therapeutic target for UC." (PMID 21304977, 2011). "The inverse correlation between IL-10 levels and DNA damage also demonstrated that the w-6:w-3 ratio (2:1) was important in reducing disease activity and colon cancer prevention associated with colitis." (PMID 20615224, 2010). "But our knowledge of how commensal-dependent TLRs, upstream of MyD88, may differentially regulate the phenotype of colitis in the IL-10-deficient host remains so far limited." (PMID 20803699, 2010). "In 7-week-old non-inflamed Il10−/− mice, increased Ido1 gene expression might also be important in the early response to commensal bacteria preceding colitis due to the deficiency of the Il10 gene." (PMID 20671959, 2010). "In DSS-induced colitis and in chronic colitis induced by IL-10 deficiency, we also observed a disappearance of the ring-shaped fluorescent stains and the aggregation of punctate fluorescent stains, which reflected the destruction of crypts and the infiltration of mononuclear cells, respectively." (PMID 20074376, 2010). "Thus, tissue from DKO mice with colitis showed increased production of pro-inflammatory cytokines compared with mice singly deficient in IL-10, mast cells, or TNF." (PMID 20808919, 2010). "Thus, systemic administration of an IKKβ-specific inhibitor reduced Stat3 activation and IL6-target gene expression and ameliorated disease in colitis-prone IL10-deficient mice." (PMID 20478049, 2010).
colitis (continued). "In addition, N297A was shown to have therapeutic activity in a murine colitis model induced by adoptive transfer of IL-10 deficient CD4+ T cells." (PMID 19172487, 2009). "To further delineate the role of bacteria in promoting the development of CAC, we mono-associated germ-free WT and Il10−/− mice with Bacteroides vulgatus (B. vulgatus), an enteric bacterium, which has been reported previously to induce only mild colitis in the Il10−/− model of IBD." (PMID 19551144, 2009). "Also, TRX significantly ameliorated DSS-induced colitis and colonic inflammation of IL-10 deficient mice." (PMID 18382663, 2008). "This strategy has been first applied to IBD, where the intragastric administration of a genetically engineered L. lactis strain producing an anti-inflammatory cytokine, the interleukin-10 (IL-10), caused a significant reduction in colitis in mice treated with DSS." (PMID 17659075, 2007). "Interleukin-10–deficient mice predisposed to colitis contained predominantly Lactobacillus johnsonii, whereas mice with an intact interleukin-10 gene lacking evidence of colitis had greater Lactobacillus species diversity and featured L. reuteri as a predominant species." (PMID 17238278, 2006). "Similarly, MNV infection of Il10-deficient mice, a subclinical colitis model, induced apparent mucosal inflammation and enhanced epithelial apoptosis and barrier disruption, but only in the presence of enteric microbiota, indicating norovirus as a microbial-context-dependent colitogenic pathogen." (PMID 41020029, 2025). "Thus, the observed IL-10 elevation in Mcpt-4-deficient colitis mice may indicate an endogenous attempt to mitigate inflammation that is otherwise exacerbated in the absence of Mcpt-4." (PMID 40697820, 2025). "In one study, the pValacDNA eukaryotic expression vector encoding IL10 was electroporated into Lactococcus lactis expressing FnBPA, and it was found that the recombinant strain could effectively inhibit the inflammatory response in a mouse colitis model." (PMID 37799603, 2023). "Although the IL-10 fusion protein and an invasive L. lactis strain carrying the IL-10 plasmid both alleviated colitis in a range of colitis models, including IL-10-deficient mice, IBD patients can have raised levels of IL-10 in serum and may not benefit from IL-10 therapy." (PMID 36012618, 2022). "Therefore, the aim of the present work was to systematically characterize the natural history of the colitis in IL-10 deficient mice from 3 to 70 weeks old, focusing on events preceding overt inflammation including microbiota disturbances and intestinal barrier dysfunctions." (PMID 36699599, 2022). "Consequently, IL-10 associated immunomodulatory reactions would be activated in lymphoid tissues by A. argyi treatment, and that such treatment would assist the attenuation of inflammation in colitis, although this postulate requires further confirmation." (PMID 35277165, 2022). "Dysregulation of IL-10 has shown to be linked with susceptibility to numerous infectious diseases such as Mycobacterium avium Infection, Helicobacter hepaticus-induced colitis, HIV, hepatitis C virus (HCV) infection and autoimmune diseases like inflammatory bowel disease." (PMID 36148228, 2022). "In contrast, we observed broad distortion of microbiota composition following onset of colitis in β7-deficient IL-10−/− mice, which may be reflective of impaired B-cell recruitment and inability to meet the demand for increased luminal SIgA, brought on by inflammation." (PMID 34433904, 2022). "Although infliximab protected IL-10−/− mice from loss of body weight, shortening of colon lengths and production of excessive pro-inflammatory cytokines and mitigated the histological signs of colitis in colon sections, its therapeutic effect was inferior to the CMV-siRT+B+I circuit." (PMID 36171212, 2022). "However, an earlier study found that Akk can cause colitis in sterile IL-10 gene-deficient mice." (PMID 36590401, 2022).
colitis (continued). "S. japonicum infection also showed potential for attenuating DSS-induced colitis in Kunming mice, a feature which has been linked to decreased Th1, Th2 and Th17 responses, characterized by a significant decrease in the serum levels of IL-6, IL-2, IL-10, IL-17, IFN-γ and TNF-α." (PMID 33692793, 2021). "IL-10-/- mice fed with standard chow diet containing piroxicam for 10 days developed colitis characterized by a significant body weight loss and severe macroscopic and microscopic colonic lesions as compared to age-matched IL-10-/- mice fed with standard chow diet free of piroxicam." (PMID 34299013, 2021). "In vivo, the administration of PADF to mice with chronic DSS-colitis reduced disease signs (i.e., body weight loss and colon shortening), and improved the histology score by diminishing the levels of pro-inflammatory cytokines and increasing the production of IL-10." (PMID 32033338, 2020). "In accordance with a central role of IL-10 mediated signals on macrophage differentiation, mice exhibiting macrophage-specific IL-10R deficiency have been demonstrated to show impaired conditioning of monocyte-derived macrophages resulting in spontaneous development of severe colitis." (PMID 31214168, 2019). "Indeed, IL-10 deficiency leads to the development of colitis in mice." (PMID 30138385, 2018). "Intestinal damage secondary to murine DSS-induced colitis, ischemia/reperfusion injury total body irradiation and infectious colitis are all associated with a robust inflammatory response, and specifically, with robust expression of the inflammatory cytokines, IL1β, IL10, and TNFα." (PMID 28257503, 2017). "Therefore, since IL-10 appears to modulate inflammasome activation, an in vivo pharmacological modulation of IL-10 in animal models of hapten-induced colitis could help to unravel the mechanisms underlying the negative regulation of inflammasome by IL-10." (PMID 28179906, 2017). "Similarly, in the context of colitis, a disease associated with the elevated production of several proinflammatory cytokines, IL-10–deficient BALB/c mice are more susceptible than IL-10–deficient C57BL/6 mice, but again the mechanisms underlying this phenotype are incompletely understood." (PMID 27549173, 2016). "To determine whether the loss of NLRP3 inflammasome function and the resulting increased susceptibility to experimental colitis were driven by changes in T cell phenotype, we assessed the expression of IL-10 in CD4+ and CD8+ T cell populations isolated from the colonic LP." (PMID 27610005, 2016). "However, no study has investigated whether this mucosal delivery of IL-10 was efficient against colitis involving other mediators than only IL-10 deficiency." (PMID 25889561, 2015). "Indeed, sustained delivery of IL-10 through adenovirus-based strategy showed better results in animal models, whether the colitis was induced by IL-10 deficiency or by chemicals." (PMID 25889561, 2015). "Notably, we found that topical delivery of a LV encoding IL-10 could suppress not only the development but also prevent relapse of DSS colitis." (PMID 24712338, 2014). "However, in IL-10 knockout mice, a line genetically susceptible to intestinal inflammation, milk fat (58% saturated fat) produced a bloom in the Proteobacteria, Bilophila wadsworthia, which resulted in a doubling of the incidence rate for spontaneous colitis." (PMID 24670791, 2014). "Importantly, we previously reported that orally administered His ameliorates intestinal inflammation in an IL-10-deficient transfer mouse colitis model by inhibiting the production of pro-inflammatory cytokines by activated macrophages through intracellular mechanisms." (PMID 22303484, 2012). "However, in IL-10 deficient mice, which spontaneously develop colitis, probiotic administration could resolve inflammation, suggesting that their protective effect could be IL-10 independent." (PMID 17375199, 2007).